WWP1 (WW domain containing E3 ubiquitin protein ligase 1)
Diseases named in the same sentence as WWP1 in open-access papers (continued):
Sharing a sentence is not in itself a finding about the gene and the disease.
myocardial ischemia (1 paper, 2023). A disorder of cardiac function caused by insufficient blood flow to the muscle tissue of the heart. "Here, we demonstrated that E3 ligase WWP1 targeting KLF15 in cardiomyocytes aggravated myocardial ischemia injury." (PMID 36593958, 2023).
oral squamous cell carcinoma (1 paper, 2020). "Pin1 interacts with Thr538-Pro of ΔNp63α and disrupts p63α-WWP1 interaction to inhibit the proteasomal degradation mediated by E3 ligase WWP1, promoting ΔNp63α-induced cell proliferation of human oral squamous cell carcinoma." (PMID 32296699, 2020).
osteoarthritis (1 paper, 2023). A noninflammatory degenerative joint disease occurring chiefly in older persons, characterized by degeneration of the articular cartilage, hypertrophy of bone at the margins and changes in the synovial membrane. "Recent studies have implied that WWP1 may involve in the development and progression of osteoarthritis." (PMID 37359559, 2023). "It is required to determine whether WWP1 could be a useful biomarker of osteoarthritis." (PMID 37359559, 2023).
pancreatic cancers (1 paper, 2025). "Although further investigation is required, WWP1 inhibitors hold promise for enhancing PI3K-AKT pathway suppression in pancreatic cancer, while simultaneously reducing the risk of resistance." (PMID 39656237, 2025). "MYC amplification, which is associated with poor prognosis and metastasis in pancreatic cancer, frequently co-occurs with WWP1 amplification." (PMID 39656237, 2025). "Furthermore, analyses using The Cancer Genome Atlas (TCGA) database revealed that the high WWP1 expression signature in pancreatic cancer is associated with poor prognosis." (PMID 39656237, 2025). "The WWP1 transcript levels were significantly elevated in pancreatic cancer tissues compared to those in normal pancreatic tissues." (PMID 39656237, 2025). "Further research is essential to identify the subclasses of pancreatic cancers that exhibit high WWP1 expression signatures." (PMID 39656237, 2025).
pancreatic ductal adenocarcinoma (1 paper, 2025). An infiltrating adenocarcinoma that arises from the epithelial cells of the pancreas. "However, the expression profiles and clinical significance of WWP1 in pancreatic ductal adenocarcinoma (PDAC) tissues remain undetermined." (PMID 39656237, 2025).
Parkinson disease (1 paper, 2024). A progressive degenerative disorder of the central nervous system characterized by loss of dopamine producing neurons in the substantia nigra and the presence of Lewy bodies in the substantia nigra and locus coeruleus. "Benserazide, a well-tolerated prodrug used in combination with Levodopa to treat Parkinson’s disease, was identified in a screen for small molecules capable of binding to the Nedd4 family members WWP1 and WWP2 and interfering with the binding of PY-containing peptides." (PMID 39459900, 2024).
preeclampsia (1 paper, 2022). Preeclampsia is a hypertensive disorder of pregnancy that is characterized by new-onset hypertension with proteinuria presenting after 20 weeks of gestation, and depending on mild or severe forms may initially present with severe headache, visual disturbances, and hyperreflexia. "Increased miR-497-5p/195-5p in the preeclampsia-affected placenta was found to suppress WWP1 expression, disturbing trophoblast proliferation, migration, and invasion, eventually aggravating preeclampsia progression." (PMID 35002524, 2022).
PTEN hamartoma tumor syndrome (1 paper, 2023). An autosomal dominant syndrome caused by pathogenic variants in the PTEN gene, characterized by hamartomas, overgrowth, neurodevelopmental disorders and an increased risk of various cancers, including breast, thyroid, and endometrial cancer. "WWP1 gain of-function mutations were observed in two groups of individuals: those with PTEN hamartoma tumor syndrome (PHTS) and those with sporadic cancer, suggesting that WWP1 can drive tumor growth." (PMID 38129384, 2023).
viral infection (1 paper, 2023). "Nevertheless, these studies suggest that WWP1 holds promise as a potential target for therapeutic interventions aimed at countering viral infection." (PMID 38129384, 2023).
cancer (53 papers, 2011 to 2026). A tumor composed of atypical neoplastic, often pleomorphic cells that invade other tissues. "Although WWP1 plays a role in several human diseases, including infectious diseases, neurological disorders, and cancers, there is emerging evidence that WWP1 is also associated with metabolic disorders." (PMID 41009733, 2025). "Gain of WWP1 function is implicated in the genetic landscape of a subset of inherited cancer patients characterized by PTEN loss and appears to drive oncogenesis in both PTEN-dependent and independent mechanisms." (PMID 40002221, 2025). "WWP1 exhibits frequent mutations, genetic amplifications, and overexpression in prevalent human cancers, including prostate, breast, colon, pancreatic, and liver cancers." (PMID 39014007, 2024). "Mutations in WWP family genes, including WWP1, have been observed in various cancers and are often associated with poor clinical outcomes (André and Springael, 1994)." (PMID 39949609, 2024). "In non-small cell lung cancer (NSCLC), the WWP1 R503W mutation has been linked to increased cancer cell proliferation and invasion." (PMID 39949609, 2024). "This review explores WWP1’s upstream regulatory molecules, downstream substrates, and associated signaling pathways in human cancers." (PMID 39949609, 2024). "The following sections explore the functions of WWP1 in cancer and their underlying mechanisms in detail." (PMID 38129384, 2023). "One notable application of PROTACs is their ability to degrade the WWP1 oncoprotein, which has been implicated in WWP1-driven cancers." (PMID 38129384, 2023). "Studies from the last two decades reveal that WWP1 is mutated, genetically amplified, and overexpressed in several human cancers, including solid tumors and hematological malignancies." (PMID 38129384, 2023). "These associations with various cancers are likely mediated by a number of different identified WWP1 target proteins but the link with Notch signalling has been little studied." (PMID 35204725, 2022). "WWP2, like WWP1, has been associated with a number of different cancers, acting as either an oncogene or as a tumour suppressor in different cell contexts." (PMID 35204725, 2022). "In this review article, we will describe the association between dysregulated WWP1 expression and clinical features of cancer patients." (PMID 34226507, 2021). "We also compared WWP1-WT versus WWP1 K740N and N745S, two germline variants that were implicated in cancer susceptibility and demonstrated to be gain-of-function mutation towards the tumor suppressor PTEN31." (PMID 33762578, 2021). "In this review article, we will describe the association between WWP1 expression and clinical features of cancer patients." (PMID 34226507, 2021). "Numerous mutations have been reported in human cancers, which can cause dysregulation of WWP1 activity." (PMID 34712671, 2021). "Overall, heightened expression and mutations of WWP1 are the two main causes of their pro-oncogenic functions in various cancers." (PMID 33418880, 2021). "Some cancer-related mutations can fully disrupt the inhibitory interactions and make WWP1 hyperactive." (PMID 34712671, 2021). "Some cancer-related mutations can result in abnormally hyperactive WWP1 proteins, which aberrantly increase polyubiquitinations of some oncoproteins or tumor suppressors and consequently promote tumorigenesis." (PMID 34712671, 2021). "The structure of fully inhibited WWP1 reveals that many WWP1 mutations identified in cancer patients result in a partially active state with increased E3 ligase activity, and the WWP1 mutants likely promote cell migration by enhancement of ∆Np63α degradation." (PMID 31320636, 2019). "The biochemical and structural information presented in this study allowed us to test the impact of some mutations that have been found in cancer patients in terms of their effect on the ligase activity of WWP1." (PMID 31320636, 2019).
cancer (continued). "Accumulating evidence has demonstrated the vital role of WWP1 as an oncogenic factor that has been found to be frequently misregulated or mutated in different human cancers, although the underlying mechanism is largely unclear." (PMID 31320636, 2019). "A natural mutation of WWP1 found in cancer cells maps to a similar interface location, though on an adjacent helix, and has been shown to cause constitutive activation of activity, perhaps by destabilizing this inactive conformation." (PMID 26701932, 2015). "Of note, aberrant expression of WWP1 is often associated with poor prognosis in several cancers." (PMID 39364720, 2025). "WWP1 is an oncogenic factor implicated in the maintenance of several human cancers." (PMID 39364720, 2025). "Additionally, phosphatase and tensin homolog (PTEN), a commonly mutated, deleted, or silenced tumor suppressor in numerous cancers, has been linked to the WWP1-PTEN axis in MYC-induced tumorigenesis and progression." (PMID 39949609, 2024). "Dysregulation of WWP1 expression and activity is associated with various pathophysiological conditions such as infectious diseases, neurological diseases, chicken muscular dystrophy, aging, osteogenic disorder, cardiac disorder, and cancer." (PMID 38129384, 2023). "WWP1 plays a role in several human diseases, including cardiac conditions, neurodevelopmental, age-associated osteogenic disorders, infectious diseases, and cancers." (PMID 38129384, 2023). "Additionally, gain of function germ line mutations of WWP1 have been identified in cancer susceptibility syndromes and in cancer patients." (PMID 33762578, 2021). "Additionally, and in line with this notion, we identified three variants that bind more avidly to the SARS-CoV-2 S protein: two rare NEDD4 variants (I843R and R877G) and the N745S germinal variant in WWP1, which was already characterized in cancer studies." (PMID 33762578, 2021). "Numerous somatic mutations occur in the WWP1 gene in different human cancers." (PMID 34712671, 2021). "WWP1 has been frequently found to be upregulated or mutated in human tumors and cancers, although the underlying mechanism remains unclear." (PMID 31320636, 2019). "Importantly, all cancer-related mutations of WWP1 within the WW–HECT packing interface led to elevated enzymatic activity, thus promoting cell migration and proliferation possibly by mediating ∆Np63α turnover." (PMID 31320636, 2019). "The crystal structure of WWP1 2L34HECT presented in this study provides a useful tool that can be used for interpreting the effects of numerous mutations (48 out of 85) found in this region in patients with cancers and other diseases." (PMID 31320636, 2019). "Furthermore, aberrant activation of the Myc/WWP1 axis is often associated with cancer progression." (PMID 40280416, 2025). "WWP1 functions as an oncogene in various cancers, with high levels often correlating with poor prognosis." (PMID 40280416, 2025). "Future studies are needed to assess the involvement of the WWP1/TXNIP crosstalk in the regulation of leukemic cell sensitivity to anti‐cancer therapies." (PMID 39364720, 2025). "While direct studies on WBP1 in cancer are limited, other WW domain-binding proteins, such as WWP1 and WBP2, have been demonstrated to play crucial roles in cancer metabolism." (PMID 40075333, 2025). "The proto-oncogene WWP1 is overexpressed in various cancers and contributes to tumor growth and poor prognosis." (PMID 39656237, 2025). "Considering that WWP1 functions as a ubiquitin ligase that targets multiple cancer-related genes, we conducted a comprehensive analysis using RNA sequencing and identified its association with the PI3K-AKT pathway in PDAC cells." (PMID 39656237, 2025).
cancer (continued). "The WWP1/HIPK3 axis modulates cancer cell chemosensitivity through the regulation of the JNK signaling pathway." (PMID 40280416, 2025). "The expression of WWP1 is upregulated in several diseases, particularly cancer: it promotes cancer progression and contributes to a poor prognosis in several human cancers." (PMID 41009733, 2025). "WWP1 is overexpressed in cancer and has been shown to increase cell proliferation and cell survival." (PMID 39059493, 2024). "Further research is required to explore the roles of WWP1 and its regulatory microRNAs in cancer pathogenesis and treatment." (PMID 39949609, 2024). "This review aims to classify WWP1’s ubiquitinated substrates, establishing a foundation for future research in cancer treatment and diagnostics." (PMID 39949609, 2024). "For the analysis of the WWP1-mediated cancer promotion mechanism, we first predicted the downstream proteins of WWP1 in UbiBrowser 2.0." (PMID 38997648, 2024). "Non-coding RNAs, transcriptional regulators, and other factors impact WWP1 expression, thereby affecting diverse cancer types." (PMID 39949609, 2024). "Given WWP1’s complex role, it is proposed as a potential therapeutic target for various human cancers." (PMID 39949609, 2024). "Regulation of WWP1 expression significantly influences various cellular processes, particularly those related to cancer." (PMID 39949609, 2024). "This section explores WWP1’s functions across different malignancies, paving the way for innovative cancer therapies." (PMID 39949609, 2024). "Studies have shown that WWP1 is frequently overexpressed or amplified in numerous cancers, promoting tumor growth, cancer cell proliferation, migration, and cell cycle progression while inhibiting apoptosis." (PMID 39949609, 2024). "WWP2, another member of the NEDD4 family, possessing similar functional domains with WWP1, was reported to be markedly correlated with tumorigenesis and progression in several cancers." (PMID 36803368, 2023). "Increased understanding of the dual roles of WWP1 can inform the development of personalized therapeutic approaches for cancer." (PMID 38129384, 2023). "The expression of WWP1 is tightly regulated by various transcriptional and posttranscriptional factors during cancer development." (PMID 38129384, 2023). "Elucidating the role of WWP1 in CYT1 degradation underscores the potential for innovative treatment modalities targeting aberrant cellular proliferation in diseases such as cancer." (PMID 38129384, 2023). "Previous studies have indicated that WWP1 plays important roles in various pathologies such as cancers, infectious diseases, and neurological diseases." (PMID 37032433, 2023). "The multifaceted and complex roles of WWP1 in various cellular processes and disease pathways render it an attractive therapeutic candidate for cancer and other diseases." (PMID 38129384, 2023). "Despite its oncogenic role in promoting cell proliferation, WWP1 has been found to exert anti-proliferative effects in some cancers, thus highlighting its diverse and complex functions." (PMID 38129384, 2023). "Studies suggest that oncogenic circular RNAs (circRNAs) and lncRNAs act as sponges for tumor-suppressive miRNAs, thus enhancing WWP1-mediated cancer progression." (PMID 38129384, 2023). "In the following sections, we will discuss the role of WWP1 in infectious diseases, neurological diseases, aging, and cancer." (PMID 38129384, 2023). "Mutation in the linker region and HECT domain disrupts the enzymatic activity of WWP1, leading to various diseases including cancer." (PMID 38129384, 2023). "Some reports suggest that WWP1 can also act as a tumor suppressor by inhibiting migration and invasion in some cancers." (PMID 38129384, 2023). "In cancer, WWP1 often exhibits overexpression or hyperactivation, a trend associated with unfavorable patient prognoses." (PMID 38129384, 2023).
cancer (continued). "Recently, many studies revealed that the abnormal regulation of WWP1 participated in many diseases, such as, neurological disorders, dystroglycan-related disorders, cardiac hypertrophy, and cancers." (PMID 35264565, 2022). "Here, we comprehensively analyzed the expression profile of WWP1 in different cancer types using GEPIA database." (PMID 34712671, 2021). "This unravels a potential therapeutic strategy for prevention and treatment of some cancers through WWP1 suppression." (PMID 34712671, 2021). "It is poorly known how WWP1 is downregulated and what exact effects it has on tumorigenesis in these cancer cells." (PMID 34712671, 2021). "Pathologically, several lines of evidence demonstrated that WWP1 expression is aberrantly expressed in a variety of human cancers." (PMID 34226507, 2021). "According to our analysis of database, in combination with previous reports, we come to a conclusion that WWP1 expression is augmented in various cancers." (PMID 34712671, 2021). "Together, these data demonstrate that WWP1 can affect TGFβ pathway in multi-dimensions to promote neoplasia and progression of several cancer types, such as PCa and NSCLC." (PMID 34712671, 2021). "The hyperactive state and oncogenic functions of WWP1 in some cancer types make it possible as a therapeutic target." (PMID 34712671, 2021). "We hope this review can stimulate the research to improve our understanding of WWP1-mediated tumorigenesis and accelerate the discovery of novel therapeutic strategies via targeting WWP1 expression in cancers." (PMID 34226507, 2021). "WWP1 has been found to promote proliferation, migration and invasion, inhibit apoptosis, and enhance cell cycle in cancer cells." (PMID 34226507, 2021). "In the future, more effective small molecules targeting WWP1 should be explored to make this hyperactive E3 ligase ease off in cancers." (PMID 34712671, 2021). "We also highlight the compounds as the inhibitors of WWP1 to improve the treatment outcomes of human cancers." (PMID 34226507, 2021). "We believe that more specific inhibitors of WWP1 will be discovered for targeted therapy of human cancer." (PMID 34226507, 2021). "Given the dysregulation and oncogenic functions of WWP1 in some cancer types, it is promising to explore some therapeutic inhibitors to tune down its activity." (PMID 34712671, 2021). "Without a doubt, in-depth investigations are necessary to validate the biological functions of WWP1 in cancer cells." (PMID 34226507, 2021). "We summarize the WWP1-mediated ubiquitinations of diverse proteins and the signaling pathways they involved, as well as the mechanisms how they affect cancer formation and progression." (PMID 34712671, 2021). "The transient overexpression of WWP1 promotes cell proliferation, while WWP1 knockdown significantly suppresses cancer cell proliferation and induces apoptosis." (PMID 33187263, 2020). "Various studies suggested the role of WWP1 as a biomarker for cancer, however, more studies need to be done in different cancer models." (PMID 29479529, 2018). "Although WWP1 has been shown to be upregulated in many human cancers, it has also been reported as downregulated in some other types of tumors, suggesting that WWP1 plays distinct roles in different tumors." (PMID 26506518, 2015). "By screening members of the NEDD4-like family ubiquitin ligases that play important roles in cancer, we have identified WWP1 as a novel negative regulator of LATS1 tumor suppressor stability." (PMID 23573293, 2013).